NEAT1 (nuclear paraspeckle assembly transcript 1)
Diseases named in the same sentence as NEAT1 in open-access papers (continued):
Sharing a sentence is not in itself a finding about the gene and the disease.
breast cancer (continued). "HIF-2α has been shown to bind to sequences upstream of the NEAT1 lncRNA promoter in MCF-7 breast cancer cells." (PMID 28327666, 2017). "The results demonstrated that SNHG6 and NEAT1 had opposite change of expression levels in breast cancer combined with primary lung cancer patients." (PMID 28938549, 2017). "In conclusion, for the first time we have identified that NEAT1 plays oncogenic roles in promoting tumorigenicity and stemness of BRCA1-deficient breast cancer." (PMID 27556296, 2016). "High expression of NEAT1 in patients with breast cancer was reported to be correlated with poor survival." (PMID 27323856, 2016). "To reveal the functional role of NEAT1 in breast cancer, we conducted a series of functional studies to examine the role of NEAT1 in the invasiveness, anchorage-independent growth and stemness of breast cancer cells." (PMID 27556296, 2016). "Consistent with findings from human breast tumor cells, Neat1 knockdown suppressed in vitro self-renewal of CSCs in mouse Brca1 mutant mammary tumors." (PMID 27556296, 2016). "NEAT1 functions as an oncogenic factor in multiple types of cancer, including breast cancer, and its expression is under the regulation of ERα signaling, the miR-449b-5p/c-Met axis, and hypoxia responses." (PMID 27556296, 2016). "NEAT1 has been shown to play an oncogenic role in prostate tumorigenesis and hypoxia-related breast cancer cell survival." (PMID 27556296, 2016). "Using expression data derived from a cohort of 2000 patients with breast cancer, patients were categorized according to NEAT1 expression." (PMID 25417700, 2015). "Here, we show that NEAT1 accelerates cell proliferation, promotes clonogenic survival and inhibits apoptosis in hypoxic breast cancer cells." (PMID 25417700, 2015). "Here, we show that NEAT1 long non-coding RNA (lncRNA) is a direct transcriptional target of HIF in many breast cancer cell lines and in solid tumors." (PMID 25417700, 2015). "This indicates that tumor NEAT1 expression is an independent prognostic marker in breast cancer patients, at least with respect to these variables." (PMID 25417700, 2015). "For example, XIST, KCNQ1OT1 and NEAT1 are there experimentally confirmed breast cancer related lncRNAs, which have been ranked 1st, 8th, and 12th in the predicted list based on the model of HGLDA, respectively." (PMID 26278472, 2015). "Here, we show the regulation of NEAT1 by hypoxia and demonstrate its generality across breast cancer cell lines and tumor models." (PMID 25417700, 2015). "The malignant behavior of tumor cells in breast cancer, hepatocellular carcinoma, laryngeal squamous cell carcinoma, lung cancer, glioma, prostate cancer, and skin cancer can be reduced by NEAT1 knockdown." (PMID 41244835, 2025). "We have identified some lncRNAs associated with breast cancer cell subpopulations already well known in the literature, such as MALAT1 and NEAT1, and highlighted some others that may be clinically relevant." (PMID 38611028, 2024). "NEAT1 could promote the growth and survival cancer cells and chemoresistance in breast cancer cells." (PMID 39479021, 2024). "However, it has been reported to be significantly downregulated in breast cancer and is likely to interact with lncRNA NEAT1, which has been found to drive the progression of various cancers including colorectal, breast and gastric cancer." (PMID 37509410, 2023). "Targeting specific lncRNAs, such as NEAT1 and lncROPM, may hold promise as therapeutic strategies to combat breast cancer, especially in cases of chemoresistance." (PMID 37958880, 2023). "Furthermore, lncRNA H19 and lncRNA NEAT1 act upon each other and respectively regulate apoptosis by targeting miR-675 and miR-204 in breast cancer." (PMID 37313458, 2023). "In breast cancer cells, NEAT1 can interact with miR-107 and regulate the expression of CPT1A." (PMID 37310654, 2023). "NEAT1 was demonstrated to have a role in tumor initiation, growth, and metastasis in breast cancer." (PMID 37624034, 2023).
breast cancer (continued). "Increased expression of LINC00473 in HNSCC; LINC00114, MINCR and PVT1 in NPC; Linc-RA1 in glioma; LINC00473and CYTOR in NSCLC; NEAT1 and LINC00958 in cervical cancer; H19 in cardiac cancer; LINC02582 in breast cancer; and TUG1 in bladder cancer were associated with radioresistance." (PMID 36323697, 2022). "In particular, in breast cancer NEAT1 stimulates the use of free fatty acids as energy source." (PMID 36182907, 2022). "Interestingly, NEAT1 is upregulated in about 65% of tumours, including breast cancer, prostate cancer, colon cancer, lung cancer, ovarian cancer, and pancreatic cancer." (PMID 35457249, 2022). "Importantly, the observed influence of NEAT1 on breast cancer cellular growth and apoptosis has been demonstrated by other groups in other breast cancer cell lines, underlining the generalizability of these findings." (PMID 35776213, 2022). "At the same time, NEAT1, which is induced by estrogen in breast cancer, can form FOXN3-NEAT1-SIN3A inhibitory factor, through the interaction with FOXN3 and SIN3A protein complex, and promote epithelial-mesenchymal transformation (EMT) and metastasis, diffusion and invasion of breast cancer cells." (PMID 34804040, 2021). "The role of NEAT1 in breast cancer has been widely investigated." (PMID 33987091, 2021). "In conclusion, our data suggest that the serum levels of PVT1, HOTAIR, NEAT1, PAI-1, and OPN could serve as promising diagnostic biomarkers for breast cancer." (PMID 33670447, 2021). "Similarly, in breast cancer, miR-211 expression is suggested to down-regulate and suppression of miR-211 facilitates lncRNA NEAT1 promoting cancer cell growth and invasion." (PMID 33482820, 2021). "NEAT1 was a prognostic marker for breast cancer, based on relapse-free survival analysis." (PMID 33987091, 2021). "In conclusion, these data revealed various mechanisms of NEAT1 in the regulation of breast cancer and suggested that NEAT1 might function as a potential biomarker in breast cancer." (PMID 34527584, 2021). "The NEAT1–ZFX–miR-493-5p axis was also an unfavorable prognostic marker of breast cancer." (PMID 33987091, 2021). "In conclusion, our results revealed that serum PVT1, HOTAIR, NEAT1, PAI-1, and OPN could be promising molecular diagnostic markers for breast cancer." (PMID 33670447, 2021). "NEAT1 is overexpressed in breast cancer and acute myeloid leukemia and may play an important role in the DNA damage pathway." (PMID 33435206, 2021). "In addition, NEAT1 is positively correlated with breast cancer stage, such that low NEAT1 levels predict good prognosis whereas high NEAT1 levels predict poor prognosis." (PMID 34711117, 2021). "Moreover, NEAT1 acts as a sponge for 146b-5p to promote the proliferation, migration, and metastasis of breast cancer cells." (PMID 34527584, 2021). "In addition, our study revealed a similar function of NEAT1 in the promotion of the EMT as reported by other groups that mainly examined breast cancer cells and lung cancer cells." (PMID 33546665, 2021). "MiR-146b-5p is a direct target of NEAT1 and inhibits also the proliferation of breast cancer cells." (PMID 34683909, 2021). "As MALAT1 and NEAT1 are consistently upregulated under hypoxia in these breast cancer cell lines, we asked if hypoxia could upregulate eNEMAL as well." (PMID 34019552, 2021). "Deregulation of the RNA-binding protein fused in sarcoma/translocated in liposarcoma (FUS/TLS) in breast cancer cells by interacting with the lncRNA nuclear paraspeckle assembly transcript 1 (NEAT1) and miR-548ar could induce cell apoptosis." (PMID 32117463, 2020). "Previous reports have demonstrated that the NEAT1 gene is transcriptionally activated by ERα in both prostate and breast cancer, and the transcript participates in a gene repressor complex that induces epithelial-mesenchymal transition (EMT) in a mouse model of ER-positive breast cancer." (PMID 31992741, 2020).
breast cancer (continued). "Such as, NEAT1 could regulate the expression of miR‐133b by acting as a ceRNA to influence cell viability and invasion in breast cancer cells." (PMID 32986920, 2020). "Luminal A breast cancers had the lowest expression of NEAT1_2 in all three cohorts." (PMID 31992741, 2020). "Also, we demonstrated that high expression of lncRNA NEAT1 suppress the expression of miR-133b in breast cancer." (PMID 31344855, 2019). "NEAT1 was found to be induced by estrogen in breast cancer cells (MCF-7), where." (PMID 31214487, 2019). "Importantly, we found that NEAT1 was up-regulated in 90% (36 of 40 paired) of breast cancer tissues compared with adjacent normal tissues, and NEAT1 levels were negatively correlated with miR-133b levels in breast cancer tissues." (PMID 31344855, 2019). "NEAT1 was also reported to promoted breast cancer cell migration and invasion." (PMID 31344855, 2019). "Our study firstly revealed that the NEAT1/miR-133b/TIMM17A axis was involved in breast cancer metastasis and might provide a potential target for breast cancer therapy." (PMID 31344855, 2019). "NEAT1 knockdown further decreased cell growth in cisplatin- or taxol-treated cells, demonstrating a synergistic effect of the combination of shNEAT1 and chemotherapeutic drugs in breast cancer." (PMID 30894512, 2019). "The expression level of NEAT1 were significantly higher in breast cancer than in normal controls." (PMID 30894512, 2019). "Breast cancer patients with high level of NEAT1 expression show low survival rate." (PMID 30046354, 2018). "Conversely, forced expression of NEAT1 enhanced cell growth, migration and invasion in endometrial cancer, papillary thyroid cancer, nasopharyngeal carcinoma, ovarian cancer, non-small cell lung cancer and breast cancer." (PMID 30374364, 2018). "Interestingly, elevated levels of FOXN3 and NEAT1 correlated with higher histological grade and poorer overall survival in breast cancer." (PMID 29732012, 2018). "It is until recently that HIF-2α is demonstrated to transactivate NEAT1 transcription under hypoxia, which promotes the formation of paraspeckles, accelerates tumor proliferation and cancer cell survival leading to poor prognosis in breast cancer patient." (PMID 28615056, 2017). "In the breast cancer, NEAT1 is required for survival of breast cancer cells via targeting miR-548." (PMID 27926523, 2017). "Neat1 had been reported to relate with breast cancer, suggesting it as a biomarker." (PMID 29312630, 2017). "Our study suggested that, NEAT1 may be used as a prognostic parameter for breast cancer combined with primary lung cancer." (PMID 28938549, 2017). "The findings revealed that PVT1, SNHG6, NEAT1 may serve as a prognostic marker for breast cancer combined with primary lung cancer." (PMID 28938549, 2017). "Notably, NEAT1 is found overexpressed in BRCA1-deficient breast cancer and promotes self-renewal abilities in breast cancer cells through epigenetically suppressing miR-129-5p, which targets to Wnt4." (PMID 28615056, 2017). "The data indicated that NEAT1 overexpression might contribute to the incidence of breast cancer combined with primary lung cancer incidence." (PMID 28938549, 2017). "NEAT1 has been reported to be involved in ovarian cancer, gastric cancer and breast cancer." (PMID 28108736, 2017). "Next generation sequencing techonology (RNA-seq), as a new technology with high precision and reliability has been applied in screening various tumor genes, such as LncRNA Transforming Growth Factor β(ATB) in breast cancer, lncRNA nuclear-enriched abundant transcript 1(NEAT1) in prostate cancer." (PMID 29296179, 2017).
breast cancer (continued). "We next examined the influence of NEAT1 on the expression of cyclin D1, a well-established human oncogene, which is over-expressed in lung cancer, breast cancer and pancreatic cancer, and over-expression of cyclin D1 is involved in malignant transformation in lung tissue." (PMID 27351135, 2016). "Moreover, our in silico correlation analysis indicates that a significant portion of breast cancer cell lines (> 70%) manifested the regulation trend of the BRCA1/NEAT1/miR-129-5p axis." (PMID 27556296, 2016). "Finally our in silico expression correlation analysis suggests the existence of the BRCA1/NEAT1/miR-129-5p axis in breast cancer." (PMID 27556296, 2016). "Using miRNA PCR arrays that detect 84 breast cancer-related miRNAs, we identified eight differentially expressed miRNAs in NEAT1-knockdown MCF10A cells, including five upregulated miRNAs (miRs-7-5p, -129-5p, -145-5p, -328-3p, -489-3p) and three downregulated miRNAs (miRs-152-3p, -199b-3p, -495-3p)." (PMID 27556296, 2016). "Moreover, we found that NEAT1 upregulation is required for the BRCA1-deficiency-driven effect on increasing the EpCAM+BCSC population and enhancing malignancies of breast cancer cells." (PMID 27556296, 2016). "For example, Neat1, which is overexpressed in advanced ovarian carcinoma and assists diagnosis, and LINC00472, high expression of which is correlated with reduced risk of relapse and death of breast cancer patients." (PMID 27485121, 2016). "To reveal how relevant the BRCA1/NEAT1/miR-129-5p signaling axis is to breast cancer, we performed in silico analysis of publicly available cancer-related expression databases and published expression data to examine the expression correlation between these three molecules." (PMID 27556296, 2016). "Furthermore, in patients with breast cancer, high tumor NEAT1 expression correlates with poor survival." (PMID 25417700, 2015). "To evaluate the clinical relevance of NEAT1 in breast cancer, we determined whether tumor NEAT1 expression levels were correlated with patient prognosis." (PMID 25417700, 2015). "We therefore determined whether the hypoxic induction of NEAT1 influenced the behavior of breast cancer both in vitro and in vivo." (PMID 25417700, 2015). "For example, NEAT1 may promote homologous recombination repair or non-homologous end joining repair pathways and affect the response of breast cancer cells to DNA damage caused by radiotherapy and chemotherapy." (PMID 39479021, 2024). "Additionally, NEAT1 downregulation improved chemosensitivity to 5-FU in breast cancer cells." (PMID 37310654, 2023). "Furthermore, based on the ROC curve results, CASC2 and NEAT1 genes may be suitable biomarkers for breast cancer diagnosis." (PMID 37706018, 2023). "Thus, our results indicate that increased expression of VIRMA may promote the expression of m6A-methylated NEAT1 that in turn triggers oncogenicity of breast cancer cells in vitro." (PMID 37208522, 2023). "To better understand the more accurate function of NEAT1 in the breast cancer and gastric cancer statuses, we designed integrated bioinformatics and experimental expression analyses to find the expression pattern of NEAT1 and related lncRNAs and mRNAs that have RNA interactions with NEAT1." (PMID 35581633, 2022). "The reason why CBX7 is lost in breast cancer cells may be ascribed to lncRNA NEAT1 targeting CBX7." (PMID 34659360, 2021). "Furthermore, our results revealed that NEAT1 could significantly discriminate between the breast cancer patients and control subjects with a sensitivity of 82%, a specificity of 80%, and an AUC of 0.83." (PMID 33670447, 2021). "In addition, NEAT1 could differentiate between breast cancer and fibroadenoma patients with a sensitivity of 80%, a specificity of 80%, and an AUC of 0.72." (PMID 33670447, 2021). "Importantly, NEAT1 was found significantly up-regulated in breast cancer tissues and cell lines." (PMID 31214487, 2019).
breast cancer (continued). "In this study, we proposed lncRNA NEAT1, which was up-regulated in breast cancer and also correlated with poor survival, could bind and even induce miR-133b degradation, thus down-regulated its expression in breast cancer cells." (PMID 31344855, 2019). "Therefore, we then investigated whether NEAT1 expression is also inversely correlated with miR-133b expression in breast cancer cells and clinical specimens." (PMID 31344855, 2019). "Besides, interaction of FOXN3 with NEAT1/SIN3A showed to repress GATA3 in breast cancer metastasis." (PMID 30894512, 2019). "Moreover, NEAT1 also positively correlates with poor survival in breast cancer patients." (PMID 27351135, 2016). "These metabolites can act through intervening in breast cancer targets such as SARM1, RGS5, BAG1, PROM2, and NEAT1." (PMID 40223933, 2025). "NEAT1 expression is upregulated in BT474, MCF-7, MDA-MB-231, MDA-MB-453, and SK-BR-3 breast cancer cells compared to the MCF10A human breast cell line, and its high expression correlates with poor overall survival in breast cancer patients." (PMID 41163216, 2025). "The exosome-derived lncRNA NEAT1 upregulated CXCL12 expression through competitively binding to miR-133b, promoted breast cancer cell migration and growth, and induced paclitaxel resistance in breast cancer cells." (PMID 38691224, 2024). "NEAT1 downregulation was shown to suppress cell proliferation in MCF-7, MDA-MB-453, MDA-MB-231, and SKBR3 breast cancer cells." (PMID 37310654, 2023). "For example, the lncRNA nuclear enriched abundant transcript 1 (NEAT1) was reported as an oncogene in various malignant tumors, including hepatocellular carcinoma, non-small cell lung cancer, and breast cancer." (PMID 37986114, 2023). "In line with our findings, a previous study demonstrated a positive correlation between NEAT1 and GAS5 in breast cancer patients." (PMID 36439973, 2023). "The NEAT1/miR-218-5p/TPD52 axis was shown to promote cell proliferation and migration of breast cancer cells." (PMID 37310654, 2023). "Alternatively, hypoxia induces the lncRNA nuclear paraspeckle assembly transcript 1 (NEAT1) in a HIF2α-dependent manner and reduces apoptotic cell death in breast cancer cells." (PMID 37583933, 2023). "Correlation of CASC2, NEAT1, and LINC00299 expression with clinicopathological features of breast cancer." (PMID 37706018, 2023). "The inhibition of NEAT1.1 and NEAT1.2 strongly suppressed cell proliferation and enhanced apoptosis in MCF-7 breast cancer cells." (PMID 37310654, 2023). "Fibro_5 cells were characterized by conserved and nuclear-enriched lncRNA (MALAT1, NEAT1), and MALAT1 modulates the expression of cell cycle-related genes in lung fibroblast and EMT-related genes in breast cancer." (PMID 35935940, 2022). "Nuclear paraspeckle assembly transcript 1 (NEAT1) is enriched in the nucleus and drives multiple cancers, including HCC, breast cancer, and colorectal cancer." (PMID 36213383, 2022). "Reduced expression of BLACAT1 in HNSCC; MALAT1, NEAT1 and PVT1 in NPC; FAM201A, PVT1 and LINC00857 in NSCLC; LINC00473, CCAT2and Rpph1 in EC; HOTAIR and LINC00958 in CRC; AFAP1-AS1 and LINC00511 in breast cancer were correlated with radiosensitivity." (PMID 36323697, 2022). "NEAT1 can upregulate many oncogenic factors, such as KLF12, Cyclin D1, ZEB1, and HMGA2, which subsequently promote the proliferation and metastasis of breast cancer." (PMID 36011001, 2022). "MIR29B2CHG, NEAT1, MALAT1, AC005332.4, NORAD, and XIST were elevated in normal breast samples than in breast cancer samples." (PMID 35756601, 2022). "For example, lncRNA NEAT1 promotes breast cancer growth by controlling miR-410-3p/CCND1 axis, demonstrating the therapeutic potential of lncRNA NEAT1." (PMID 35909905, 2022). "For instance, lncRNA NEAT1 upregulated the expression of EZH2 and promoted breast cancer growth by inhibiting miR-101 expression." (PMID 34399848, 2021).